AR (androgen receptor)
Diseases named in the same sentence as AR in open-access papers (continued):
Sharing a sentence is not in itself a finding about the gene and the disease.
cancer (continued). "Despite reaching the CRPC stage, the cancer continues to rely on AR signaling for growth as evidenced by the upregulation of AR expression." (PMID 38255286, 2024). "The ERBB4 gene in “Proteoglycan in Cancer”, the AR gene in “Pathways in Cancer” and “Estrogen Response Early” pathways, were upregulated in the transition from ovarian epithelial cells to LGSC." (PMID 38534733, 2024). "Castration-resistant prostate cancer (CRPC) is an advanced form of the disease in which cancer cells can survive despite androgen deprivation, frequently by restoring AR activity." (PMID 39253786, 2024). "The mechanism of ADT resistance includes mutation, amplification, and crosstalk between the cellular signal pathways related to the androgen receptor (AR) gene, and the androgen autocrine system of cancer cells." (PMID 39517121, 2024). "Paramount in this exchange is our unique visualisation of AR intercellular traffic, which has profound significance due to the known consequences of androgen biology in cancer progression and response to treatment." (PMID 39858418, 2024). "AR-V7 and AR were successfully detected in as little as 12 pure cancer cells, 6 cancer cells mixed with 1,000 WBCs (0.6% purity), and 9 cancer cells mixed with 3,000 WBCs (0.3% purity)." (PMID 38627648, 2024). "We find that the ANKRD1 gene is specifically expressed and upregulated in CAFs of various cancer types, is a direct target of AR suppression, and is both required and sufficient for CAF activation." (PMID 38310103, 2024). "The role of AR in controlling the transcription and translation of critical metabolic and trafficking machinery is important, and therefore its transfer between cancer cells and other cells adds another dimension to this critical cell biology." (PMID 39858418, 2024). "For advanced forms of the disease, androgen deprivation therapy (ADT), targeting the activity of androgen receptor (AR) that is driving the cancer, is initially effective." (PMID 38218884, 2024). "Antiandrogens like abiraterone, enzalutamide and apalutamide block the AR or synthesis pathways, preventing testosterone from stimulating cancer growth and increasing survival in advanced PC patients." (PMID 39351434, 2024). "An earlier study has shown that miR-363 is induced in AR-expressing breast MDA-MB-453 cancer cells and that this miRNA targets the mRNA; hence, the expression of IQ motif and WD repeats-1 (IQWD1)." (PMID 38339416, 2024). "In castration-resistant prostate cancer, inhibition of androgen receptor (AR) induces HR defects and confers PARPi sensitivity, suggesting that AR signaling promotes cancer cell survival by enhancing HR." (PMID 39007266, 2024). "No currently available phase III trial compared docetaxel vs. androgen receptor pathway inhibitors (ARPI) regarding cancer-control outcomes in metastatic hormone-sensitive prostate cancer (mHSPC)." (PMID 39731623, 2024). "With time and selective treatment pressures, the cancer develops less reliance on androgen receptor‐dependent signalling." (PMID 38371200, 2024). "Eventually the cancer becomes resistant due to adaptive responses of AR-signaling and activation of other signaling mechanisms." (PMID 38589887, 2024). "When AR becomes dysregulated it is the driving force of many human diseases including androgen insensitivity syndrome, Kennedy's Disease, and various cancers." (PMID 38554103, 2024). "Collectively, these experimental data validated the links a, b, and c proposed in our working model and demonstrated the effect of flutamide, via the expression of miR-449a and miR-449b-5p, on the suppression of CSF1R and AR and cancer cell migration." (PMID 39622842, 2024). "This malignancy, characterized by multiple distinct cancer foci and varying androgen receptor (AR) expression levels, has been at the forefront of therapeutic research for decades." (PMID 38396800, 2024).
cancer (continued). "Prior research on sex hormone signaling and cell metabolism in cancer showed androgens signaling through the AR altered cell metabolism." (PMID 39404231, 2024). "Given NSD2 inactivation resulted in disruption of the cancer-specific AR cistrome, we set out to phenotypically characterize NSD2-deficient PCa cells." (PMID 39251788, 2024). "AR-V7-Targeted Immunotherapy: AR-V7-Targeted Immunotherapy (MVI-118) is a DNA vaccine for metastatic prostate cancer, promoting a CD8+T cell-mediated immune response against AR-overexpressing cancer cells." (PMID 39199550, 2024). "Semaphorin 3C (SEMA3C) is a secreted autocrine growth factor that drives growth and treatment resistance of prostate and other cancers and is known to be regulated by both AR and FOXA1." (PMID 38528115, 2024). "The significant activity against the LAPC-4 cancer cell line was in accordance with the potential binding to the androgen receptor." (PMID 39345716, 2024). "By effectively inhibiting KIF20A, Paprotrain disrupts the autocrine activation mechanisms of the androgen receptor (AR), a key driver of cancer proliferation in prostate cells that have become resistant to traditional androgen-deprivation therapies." (PMID 39272816, 2024). "Concordantly, a dual NSD1/2 PROTAC degrader, called LLC0150, showed selective potency in AR-dependent as well as NSD2-altered human cancers." (PMID 39251788, 2024). "Because of its importance in cancer, AR has been well studied at the protein level, but there is still much to be learned about its regulation at the mRNA level." (PMID 38554103, 2024). "Androgen receptor (AR) is a transcription factor expressed in various normal tissues and is a therapeutic target for prostate and possibly other cancers." (PMID 38790919, 2024). "In AR-independent contexts, we posit that effects on other CDK9 downstream targets are the dominant mechanism underlying CDKI-73’s anti-cancer activity." (PMID 39117800, 2024). "In the current study, we observed a negative correlation between ITGBL1 protein expression and FBLN2 protein expression in AR‐GC cell lines and GC cancer tissues." (PMID 38332530, 2024). "It is important to note that the specific relationship between GR or AR with certain pioneer factors can depend on the progression state of the cancer cells." (PMID 39027480, 2024). "Various PCa hormone therapies, such as androgen receptor (AR)-antagonists or supraphysiological androgen level (SAL) reduce cancer cell proliferation." (PMID 38589887, 2024). "Aside from AR, another top TF in Black men, ESR1 (estrogen receptor alpha), is a sex steroid hormone receptor implicated in hormone-driven cancers, such as prostate and breast." (PMID 39044302, 2024). "They bind directly to the active site of the androgen receptor, impeding its nuclear translocation, inhibiting DNA binding, and, consequently, reducing androgen receptor-mediated transcription and cancer growth/progression." (PMID 38667168, 2024). "Once mutated, SPOP impairs substrate binding and polyubiquitination, thereby affecting various cancer-related pathways including AR signaling, DNA repair and methylation, cancer metabolism, and immunity." (PMID 39748950, 2024). "In the present study, we utilized the human AR-QL (23 Q) construct to overexpress AR and suppress cancer growth through decreasing FOXP4 expression." (PMID 38890503, 2024). "Due to the critical role of the androgen receptor (AR) in carcinogenesis and progression of cancer, targeting AR signaling has become mainstream approach for PCa therapy." (PMID 38898473, 2024). "Here, based on the observation that canonical AREs are depleted in the AR cistromes of human cancers, we designed an experimental system to modulate genes specifically controlled by AREs in a genome-wide fashion." (PMID 39672812, 2024). "A plethora of studies have reported the pivotal role of AR in the initiation and advancement of various types of cancers." (PMID 38372868, 2024).
cancer (continued). "Accumulating data strongly suggest that AR signaling affects the immune response in various physiological and pathological conditions including allergic disease, autoimmune disease, and cancer." (PMID 38349455, 2024). "Targeting the AR has been studied as a potential cancer therapy, but with limited efficacy due to drug resistance." (PMID 37903548, 2024). "Silibinin exerts its anti-cancer effects by impeding cell proliferation through targeting the androgen receptor (AR)." (PMID 39199550, 2024). "For example, myelocytomatosis (MYC) is a notorious oncoprotein overexpressed in most of human cancers, and androgen receptor (AR) and forkhead box A1 (FOXA1) are pioneer factors in PRAD." (PMID 39436262, 2024). "The era of targeted cancer therapy was heralded by drugs binding to the estrogen receptor (ER) or androgen receptor (AR), and later by the emergence of small-molecule kinase inhibitors." (PMID 38255778, 2024). "Mechanisms of resistance include AR gene amplification and overexpression, where cancer cells become more sensitive to low androgen levels due to an increased number of AR gene copies or higher AR protein levels." (PMID 39184676, 2024). "When AR signaling is inhibited by therapies, cancer cells can adapt by activating alternative pathways that allow them to survive and proliferate." (PMID 39184676, 2024). "The AR regulates proliferation, cell growth, and differentiation, and its role in the expansion and evolution of human cancers of importance." (PMID 37903548, 2024). "These therapies use small molecules to degrade the AR and decrease its cancer-promoting activities, providing an alternative to traditional inhibitors that focus solely on blocking AR signaling." (PMID 39512805, 2024). "These MACC constructs represent tools to modulate ARE-containing regulatory elements, reveal and manipulate distinct subsets of AR-responsive enhancers, and interrogate cancer and normal-specific signaling pathways, with clear applicability to human specimens." (PMID 39672812, 2024). "Here, we report that p300 and CBP are requisite HATs that define the active AR enhanceosome and hyperacetylate histone H2B N-terminus (H2BNTac) to drive a unique oncogenic transcriptome and promote cancer cell proliferation." (PMID 38586029, 2024). "Using the KEGG database, we identified several androgen-regulated pathways that are affected by both AR and HIRA KO, including cancer- and metastasis-associated pathways, as FoxO, TNF, TGF-beta, PI3K-Akt, MAPK and Wnt." (PMID 37638746, 2023). "Cell culture and animal models reiterate the contributions of androgens and/or AR to the development of cancer." (PMID 37626712, 2023). "Epigallocatechin Gallate (the most abundant Catechin in green tea) inhibits CaP by promoting cancer cell death, suppressing the activation of agonist-dependent AR and its regulated genes." (PMID 37895357, 2023). "When TOMM20 was depleted, PCa cells underwent EMT, acquired the characteristics of cancer stem-like cells, and developed resistance to AR antagonists." (PMID 37563661, 2023). "The progression of PCa subtypes is androgen-receptor-dependent, and several cancer-specific molecules, including mucins, are found aberrantly overexpressed in PCa." (PMID 36980526, 2023). "Among the 3 cases for which AR status differed in the primary cancer and BrM, AR was “gained” in the BrM in one case and “lost” in the BrM in two cases." (PMID 37345085, 2023). "Although the relationship between the expression of PD-L1 and the level of AR is controversial in cancers, PD-L1 probably controls androgen-mediated cancer behaviors through integrins." (PMID 37681860, 2023). "One approach to treat this type of cancer is the use of drugs that inhibit the androgen receptor (AR)-dependent signalling pathway." (PMID 37176840, 2023).
cancer (continued). "Considering that PCa is androgen dependent, particularly at the early stage of cancer, the inhibition of AR signaling via androgen deprivation therapy (ADT) is used as the first-line treatment." (PMID 38155939, 2023). "Our prostatectomy tissue analysis showed a positive relationship with AR and SLPI expression, which are basically HNPC and AR‐dependent cancers." (PMID 36812122, 2023). "Based on the tabulated three studies and the current series, AR is expressed in 64% of all reported endometrial malignancies as opposed to the findings in our study alone where 85% of the cancers have AR expression." (PMID 37725629, 2023). "This induces a paradoxical cancer cell death via over-stabilizing AR, preventing full relicensing in the next cell cycle." (PMID 37189723, 2023). "Activation of androgen receptor (AR) signaling, through both hormone-dependent and -independent mechanisms, promotes cancer progression." (PMID 37386128, 2023). "In PC, the AR-signaling axis promotes growth and the epithelial-to-mesenchymal transition (EMT), a hallmark of metastatic aggressive cancer." (PMID 37174018, 2023). "Co-cultured putative THCs were also less sensitive to AR signaling inhibitor (ARSI) than parental cancer cells, suggesting that these cells underwent transcriptomic changes, shifting from an AR-dependent to AR-independent phenotype." (PMID 37848444, 2023). "SENP1 inhibits apoptosis, and increases angiogenesis, estrogen and androgen receptor transcription and c-Jun transcription factor, proliferation, growth, cell migration, and invasion of cancer." (PMID 37502217, 2023). "We propose that Sigma1 serves as a regulatory hub at the intersection of an AR-driven autophagy-LD-oxidative stress response in cancer cells." (PMID 37874216, 2023). "Targeting PC beyond the AR-signaling axis is clinically beneficial and the development of novel therapeutics or cross-application of current therapeutics used in other cancers can expand existing PC treatment options." (PMID 37174018, 2023). "The ability of an anti-cancer molecule to simultaneously target aromatase, ERs or AR is, from a clinical point of view, very relevant, as these are the main therapeutic targets for these types of tumors." (PMID 36677847, 2023). "An investigation of AR gene expression’s impact on clinical features and the progression of PTC demonstrated an association with high cancer risk and extrathyroidal extension in PTC." (PMID 37190127, 2023). "The expressions of ERβ and AR in the stroma were correlated with the expressions of their respective receptors in cancer cells." (PMID 37509283, 2023). "Their visionary studies established that PCa is a hormonally dependent cancer and that limiting AR activity by reducing testosterone levels is efficacious in limiting disease." (PMID 37626712, 2023). "miRNAs are reported to be deregulated in various cancers, specifically in BC and in different BC subtypes (including ER−/AR+ ones)." (PMID 37626796, 2023). "Further studies are necessary to establish the relationship between AR coregulators and their impact on cancer progression in HR+ BCa." (PMID 38203649, 2023). "In various cancers, the expression of the AR is negatively correlated with the overall immune composition and is inversely associated with PD-L1 expression." (PMID 37681860, 2023). "When TOMM20 was depleted, the PCa cells underwent EMT, acquired the characteristics of cancer stem-like cells, and developed resistance to AR antagonists." (PMID 37563661, 2023). "This article aims to review the mechanisms that allow cancer cells to switch from an AR-positive to an AR-negative disease, focusing on potential strategies to overcome these mechanisms and successfully resensitize these CRPC cells to antiandrogen therapy." (PMID 37189723, 2023).
cancer (continued). "This has resulted in the creation of a whole range of modern drugs that significantly improve the results of cancer treatment (e.g., estrogen receptor (ER) and androgen receptor (AR) antagonists, BCR-ABL, HER2, EGFR inhibitors, etc.)." (PMID 38136555, 2023). "We for the first time reported a novel mechanism by which the autophagic degradation of TOMM20 resulted in drug resistance to AR antagonists by promoting the acquisition of cancer stem-like cell characteristics." (PMID 37563661, 2023). "We aimed to analyze androgen receptor signaling in the maintenance and self-renewal of different types of cancer stem cells and its action on the expression of transcription factors and surface markers associated with stemness." (PMID 37894767, 2023). "The AR is a known cancer gene in the COSMIC database, and mutation of AR can lead to a variety of androgen-sensitive diseases." (PMID 38310436, 2023). "As DDR activation can be mediated in both AR-dependent and independent manner, these ASIs cannot radiosensitize AR-independent cancer cells." (PMID 36959798, 2023). "We propose that the influence of PI5P4Kα on lysosomal mTORC1 is responsible for stress activation of AR and exposes survival vulnerability in cancer." (PMID 36724278, 2023). "Restoring AR in cancer cells increases ADAR2 expression and diminishes circRNA generation, which finally resulted in interruption of R-2HG effect." (PMID 37369946, 2023). "The double knockdown of AR and PKA-RIα increased caspase-3 activity (associated with cancer cell apoptosis) by 17- or 18-fold, significantly more than the single knockdown (AR, 9- or 11-fold; PKA-RIα, 7.5-fold)." (PMID 37830741, 2023). "More interestingly, GSVA analysis also showed that many cancer hallmarks were dysregulated between siControl and siMETTL3 groups, with a noticeable unique pattern in LNCaP (AR+) and DU145 (AR-) cells." (PMID 37675218, 2023). "Basically, androgen/androgen receptor (AR) signaling is crucial for both normal prostate development and tumorigenesis which regulates a series of cancer biological processes including cell proliferation and metastasis." (PMID 37251950, 2023). "This type of cell death is increasingly studied in the context of cancer in line with non-coding RNAs, as well as recently—in particular—in the ER−/AR+ BC subtype." (PMID 37626796, 2023). "On the other hand, simvastatin alone or in combination with enzalutamide lowered AR expression in enzalutamide-resistant cancer cells." (PMID 36674430, 2023). "While they have specifically reported the expression of AR in different types of uterine malignancies, it is difficult to accurately extract and correlate the data to ER and PR for the same types of cancers." (PMID 37725629, 2023). "One class of currently used PCa drugs, anti-androgens, are competitive AR antagonists that target the androgen signaling pathway by competing with dihydrotestosterone and thereby blocking expression of genes involved in cancer promotion." (PMID 37046780, 2023). "Although cancer stage-dependent roles of AR have been suggested, the reasons for such inconsistency have not been well explained." (PMID 36746917, 2023). "Evidence revealed that the differential expression of the AR and ER plays a reverse role in cancer progression in ER-positive breast cancer." (PMID 37681860, 2023). "Some of these new AIs, in addition to acting on aromatase, have the ability to modulate ERα (selective ER modulator, SERM), as well as the androgen receptor (AR), acting as multi-target drugs in cancer cells." (PMID 36677847, 2023). "The main mechanism of CRPC is believed to be the persistent activation of AR signaling in cancer cells, even in the presence of ADT." (PMID 36902032, 2023).